Y_RNA (Y RNA )
Gene: Miscellaneous RNA gene on chromosome 10 (34,201,979 to 34,202,074, reverse strand). Ensembl gene ENSG00000199200.
Homologues: Orthologues: chimpanzee Y_RNA (96% identical). Paralogues in human: RNY4P10 (85% identical), RNY4P14 (85% identical), RNY4 (84% identical), RNY4P6 (83% identical), RNY4P7 (83% identical), RNY4P24 (82% identical), Y_RNA (82% identical), RNY4P13 (81% identical), RNY4P19 (81% identical), RNY4P9 (81% identical), Y_RNA (81% identical), RNY4P25 (80% identical), and 88 more.